HMGB1 (high mobility group box 1)
Diseases named in the same sentence as HMGB1 in open-access papers (continued):
Sharing a sentence is not in itself a finding about the gene and the disease.
peritonitis (continued). "In this study, we first demonstrated a significant elevation of HMGB1 in PDE of PD patients with clinical peritonitis." (PMID 23359306, 2013). "In addition, serum HMGB1 levels begin to rise significantly 18 h after surgery to induce peritonitis, while specific inhibition of HMGB1 activity 24 h after surgery can significantly improve the survival rate of mice." (PMID 40338919, 2025). "The serum and peritoneal fluid HMGB1 levels peak in the early stage of acute peritonitis and gradually decrease with treatment, suggesting that HMGB1 may be used as a biomarker to evaluate peritoneal status and therapy response." (PMID 33140586, 2021). "In the present study, we assessed the protein levels of acetylated HMGB1 in the PDE of patients with peritonitis and determined the role of acetylated HMGB1 in LPS-induced mesothelial cells damage using HMrSV5, primary peritoneal mesothelial cells and acute peritonitis in mice." (PMID 30539006, 2018). "Serum levels of HMGB1 have been associated with micro-inflammatory states in continuous ambulatory peritoneal dialysis (CAPD) patients, and inhibition of HMGB1 has a protective effect on peritoneal function in experimental models of peritonitis." (PMID 29033853, 2017). "HMGB1 level of the patients with peritonitis was higher than healthy controls." (PMID 26502877, 2015). "Since elevated expression of HMGB1 in PDE was associated with the presence of PD-related peritonitis, we further evaluated whether HMGB1 could play a role in peritoneal function during peritonitis." (PMID 23359306, 2013). "In this study, we hypothesized that HMGB1 levels would be elevated in PDE and associated with peritonitis in PD patients." (PMID 23359306, 2013). "Importantly, dynamic observation of HMGB1 levels in peritonitis patients showed that high levels of HMGB1 were evident at the onset of peritonitis, gradually diminished and barely captured on day 7 after effective antibiotic treatment." (PMID 23359306, 2013). "Thus, we propose that blockage of HMGB1 might represent a potential therapeutic strategy in PD-related peritonitis." (PMID 23359306, 2013). "Our study demonstrates that elevated HMGB1 levels in PDE during PD-related peritonitis, at least partially, from peritoneal mesothelial cells, which may be involved in the process of PD-related peritonitis and play a critical role in acute peritoneal dysfunction." (PMID 23359306, 2013). "However, the potential role and source of HMGB1 in the peritoneal dialysis (PD) effluence of patients with peritonitis are unknown." (PMID 23359306, 2013). "However, it is unclear whether HMGB1 can be expressed and released by mesothelial cells during peritonitis." (PMID 23359306, 2013). "Taken together, these findings suggest that increased PDE HMGB1 levels are associated with the severity of PD related-peritonitis, and LPS, endotoxin from Gram-negative bacteria may play additional direct role in stimulating HMGB1 secretion." (PMID 23359306, 2013). "Regulation of HMGB1 acetylation by suppressing JNK1 activity represents a strategy for protection against LPS-induced injury in peritoneal mesothelial cells and has profound implications for the treatment of human PD-related peritonitis." (PMID 30539006, 2018). "Importantly, there was a significant positive correlation between PDE levels of HMGB1 and TNF-α, IL-6, as well as WBCs counts during peritonitis." (PMID 23359306, 2013). "Further, there was a significant positive correlation between HMGB1 levels and WBC counts (r = 0.86, P<0.01), TNF-α level (r = 0.75, P<0.01) as well as IL-6 level (r = 0.81, P<0.01) in PDE of patients with peritonitis." (PMID 23359306, 2013). "In conclusion, our study reveals that HMGB1 levels in PDE are elevated and may play a critical role in peritoneal dysfunction during PD-related peritonitis." (PMID 23359306, 2013). "Taken together, these findings indicate that the HMGB1 levels in the PDE may be related to the process and severity of PD-related peritonitis." (PMID 23359306, 2013).
peritonitis (continued). "Moreover, acetylation of high mobility group box-1 (HMGB1) by the JNK1 signaling pathway was observed to be able to promote lipopolysaccharide induced apoptosis via elevating the expression of Bax and cleaved-caspase 3 in peritoneal mesothelial cells in a peritonitis model." (PMID 36014323, 2022). "However, the potential role of HMGB1 in PD-related peritonitis has not been investigated." (PMID 23359306, 2013). "However, it has never been investigated whether HMGB1 levels are elevated in PDE of patients with peritonitis." (PMID 23359306, 2013). "Given that HMGB1 is released by a variety of activated immune and non-immune cells and peritonitis can cause injury to mesothelial cells, it would be of interest to know whether the elevated HMGB1 in PDE of patients with peritonitis can be directly released from damaged peritoneal mesothelial cells." (PMID 23359306, 2013). "We found significant elevations in the peritoneal concentrations of interleukins 6, 8, 10, HMGB-1, and MCP-1 in all patients with secondary peritonitis at the moment of surgery; however, no clear correlation could be made based on this data with patient evolution." (PMID 37441100, 2023).
vasculitis (13 papers, 2012 to 2026). "To further investigate the role of HMGB1 in the pathogenic mechanism of vasculitis, we investigated the anti-inflammatory effects of HMGB1 blockades (including anti-HMGB1 mAb and glycyrrhizin) in a mouse model of a cutaneous reverse passive Arthus (RPA) reaction." (PMID 33133061, 2020). "In our research, the anti-inflammatory effects of HMGB1 blockades stems from an understanding of the biological basis of the HMGB1 inflammation, and we further investigate the role of HMGB1 in the pathogenic mechanism of vasculitis in a mouse model of cutaneous reverse passive Arthus (RPA) reaction." (PMID 33133061, 2020). "HMGB1 may play an important role in the pathogenic mechanism of vasculitis." (PMID 33133061, 2020). "Here, we evaluate the dynamics of HMGB-1 and therapeutic effects of PSL on HMGB-1-mediated inflammatory pathways on KD vasculitis in vitro." (PMID 34079539, 2021). "In this study, a HMGB1 blockade was used to treat vasculitis in a mouse model of cutaneous vasculitis." (PMID 33133061, 2020). "It meant that a HMGB1 blockade can effectively improve the clinical and pathological manifestations of vasculitis in mice." (PMID 33133061, 2020). "That means that a HMGB1 blockade can effectively inhibit the infiltration of inflammatory cells and the expression of inflammatory cytokines in the skin lesions of vasculitis mice." (PMID 33133061, 2020). "It was once again demonstrated that glycyrrhizin acts as an inhibitor of HMGB1 and also has an inhibitory effect on vasculitis." (PMID 33133061, 2020). "HMGB1 plays a significant role in the course of ischemia–reperfusion injury and vasculitis, and increased concentrations of HMGB1 have been documented in sick dogs." (PMID 29686994, 2018). "Further analysis found that urinary levels of HMGB1 correlated with erythrocyte sedimentation rate (r=0.354, p=0.012), C-reactive protein (r=0.289, p=0.042), and Birmingham Vasculitis Activity Score (r=0.350, p=0.013)." (PMID 25884225, 2015). "Inhibiting extracellular HMGB-1 may also inhibit the over-activated innate immune system, thus offering potential relief from or prevention of severe KD vasculitis." (PMID 34079539, 2021). "In general, we have experimentally demonstrated that HMGB1 is closely related to the pathogenesis of vasculitis, and that the HMGB1 blockade can significantly improve the inflammatory response of vasculitis, resulting in a more effective, safe, and potentially new treatment for vasculitis." (PMID 33133061, 2020). "Our results indicated that HMGB1 blockades (anti-HMGB1 mAb and glycyrrhizin) obviously extenuated the severity of vasculitis skin damage and improved the histological evolvement of inflammatory cells infiltration, vascular fibroid necrosis, and vasodilation in a cutaneous RPA reaction mouse model." (PMID 33133061, 2020). "In systemic vasculitis, high serum HMGB1 levels were observed in Kawasaki disease, immunoglobulin (Ig)A vasculitis, and in patients with antineutrophil cytoplasmic antibody (ANCA)-associated vasculitis, especially in granulomatosis with polyangiitis (GPA) with granulomatous manifestations." (PMID 26062541, 2015). "Moreover, Nucleotide-binding oligomerization domain-like receptor family, pyrin domain-containing 3 (NLRP3)-dependent endothelial cell pyroptosis via HMGB-1/RAGE/cathepsin B signaling may contribute to coronary artery endothelial cell (CAEC) damage in KD vasculitis." (PMID 34079539, 2021). "Therefore, our study also supports the hypothesis that extracellular HMGB-1 is possibly up-regulated to act as a functional cytokine influencing inflammation and the innate immune response, and that it may thus contribute to the pathogenesis of KD vasculitis." (PMID 34079539, 2021). "The urinary levels of HMGB1 correlated with erythrocyte sedimentation rate (ESR) (r = 0.354, p = 0.012), C-reactive protein (CRP) (r = 0.289, p = 0.042), and Birmingham Vasculitis Activity Score (BVAS) (r = 0.350, p = 0.013)." (PMID 25884225, 2015).
vasculitis (continued). "The HMGB-1/RAGE signaling pathway in endothelial cells also induces cathepsin B activation, subsequently inducing canonical pyroptosis via NLRP3 inflammasomes in KD vasculitis." (PMID 34079539, 2021). "Significant amounts of research evidence show that NETs may contain alarmins such as HMGB1 and LL39 and enhance the rate of autoantibody production in people with vasculitis 34,73,74." (PMID 33746569, 2021). "In addition, HMGB1 enhanced the TLR9 levels and proliferation of B cells in plasma cells from PBMC of patients with AAV, and the latter was positively correlated with Birmingham vasculitis activity score." (PMID 35250993, 2022). "Our findings suggest that extracellular HMGB-1 plays an important role in mediating KD pathogenesis and that PSL treatment during the acute phase of KD may ameliorate HMGB-1-mediated inflammatory responses in KD vasculitis." (PMID 34079539, 2021). "However, the function and mechanism of HMGB1 in vasculitis has not been clearly stated." (PMID 33133061, 2020).
Cachexia (12 papers, 2020 to 2025). Severe weight loss, wasting of muscle, loss of appetite, and general debility related to a chronic disease. "The blood concentration of HMGB1, elevated in patients with cachexia, is associated with TNFα concentration and is well correlated with sarcopenia in skeletal muscle cancer." (PMID 39125651, 2024). "Both mouse and in vitro cachexia models showed that CT reduced oxidative stress, inhibited autophagy and apoptosis, improved oxidative phosphorylation and the suppression of high mobility group box-1 production, and improved sarcopenia and muscle maturity." (PMID 39796128, 2024). "Consistently, HMGB1-ablated CT26 cells revealed unable to induce cachexia in the host mice and similar results were otained treating the animals with a HMGB1 inhibitor." (PMID 38424339, 2024). "Our data showed that both in vitro cachexia models and HMGB1 treatment reduced autophagy and the expression of mitophagy-related proteins such as PINK1 and Parkin." (PMID 39000167, 2024). "In our previous study, we found that serum tumor necrosis factor (TNF)-α and high-mobility group box (HMGB)-1 were increased in cachexia patients." (PMID 33110478, 2020). "In the cachexia group, HMGB1 and TNFα increased by 1.8 times and 2.3 times, respectively, compared to those in the control group." (PMID 33110478, 2020). "Further examination of mitochondrial DNA deletion in skeletal muscle when the mouse cachexia model was treated with neutralizing antibodies against HMGB1 and TNFα showed mitochondrial DNA deletion in the non-antibody-treated group but not in the antibody-treated group." (PMID 39000167, 2024). "We employed an in vitro cachexia model using mouse cancer ascites, which contained TNFα and HMGB1." (PMID 39796128, 2024). "In conclusion, we found that exosomes containing HMGB1 could induce muscle wasting and serum HMGB1 was elevated in cachexia patients." (PMID 34867338, 2021). "Finally, HMGB1 inhibitor glycyrrhizin was utilized to relieve cachexia in CT26 cachexia mouse model." (PMID 34867338, 2021). "Expression of RAGE, a receptor for HMGB1, was increased in the cachexia group." (PMID 33110478, 2020). "In our mouse cachexia model, TNFα and HMGB1 in ascites and serum were increased." (PMID 33110478, 2020). "Also, we demonstrated that serum HMGB1 was elevated in patients with cachexia." (PMID 34867338, 2021). "However, there are few studies on the relationship between HMGB1 and cachexia at present." (PMID 34867338, 2021). "However, there are relatively few reports on the relationship between HMGB1 and cachexia." (PMID 34867338, 2021). "The measurement of their blood concentrations in our mouse cachexia model revealed increased IL6, TNFα, and HMGB1 concentrations in the CD group." (PMID 39125651, 2024). "In this study, we found that tumor-derived exosome was a cachexia factor in vitro and CT26-EVs contained a high level of HMGB1." (PMID 34867338, 2021). "Surprisingly, even if glycyrrhizin is known to inhibit HMGB1, which seems increased in plasma and muscles of cachectic C26 mice but not in muscles of LLC-bearing ones, it is still not clear whether the beneficial effects of this molecule against cachexia are related to the inhibition of HMGB1." (PMID 33255345, 2020).
dementia (12 papers, 2016 to 2025). Loss of intellectual abilities interfering with an individual's social and occupational functions. "HMGB1 levels are also increased in the cerebrospinal fluid of individuals with AD and associated with rapid progression of dementia." (PMID 40046779, 2025). "When annotated through the Disease Ontology (DO) database, one gene out of 97—HMGB1 (rs1020625837)—was classified as related to AD-caused dementia." (PMID 37175659, 2023). "However, only six of these genes emerged to be associated with AD in a certain way: HMGB1, which is related AD dementia according to ‘Disease Ontology’; KANSL1; BAZ2B; EHMT1; SIRT1; and CTBP1, which are associated with AD according to the literature data." (PMID 37175659, 2023). "Thus, TLR4 activation by AGE or HMGB1 can increase the risk of dementia trough promoting brain-insulin resistance." (PMID 37373216, 2023). "However, in a group of AD patients, upregulation of HMGB1 levels was associated with a rapid progression of dementia, further suggesting that CSF levels of HMGB1 might represent a marker of neurodegenerative progression." (PMID 32046119, 2020). "Analysis of HMGB1 levels in the cerebrospinal fluid of AD patients indicated that higher concentrations of HMGB1 correlate with accelerated dementia progression." (PMID 39796257, 2025). "Interestingly, the patient with the highest levels of HMGB1 in the CSF (AD05) showed a rapid progression of dementia." (PMID 27557632, 2016). "Also, it had also been demonstrated that HMGB1 could serve as a ligand for α-synuclein, binding preferentially to α-synuclein aggregates or presenting in LBs just as identified in brain tissue of dementia with LBs or PD patients." (PMID 28197072, 2017). "Therefore, anti-HMGB1 antibody might be developed to a DMT for multiple types of dementias including mixed pathologies of Aβ and TDP43 frequently found in sporadic cases of dementia." (PMID 34385591, 2021).
dengue (12 papers, 2012 to 2022). "Due to the previous association between nitric oxide (NO) and high mobility group box 1 (HMGB1) in severe dengue, these two pro-inflammatory markers were also considered in our investigation." (PMID 32486462, 2020). "One of the molecules that could be associated with ED and the severity of dengue is the high mobility group 1 protein (HMGB1), also known as amphoterin or HMG1." (PMID 36016387, 2022). "Inhibition of dengue virus infection by the chemical resveratrol through blocking the nuclear to cytoplasmic transport of HMGB1, leading to the accumulation of HMGB1 in the nucleus." (PMID 36139393, 2022). "In a previous report, dengue cases showed increased levels of HMGB-1 in several tissues that revealed the important role of this protein in dengue pathogenesis." (PMID 35041718, 2022). "With regard to dengue, the drug can inhibit HMGB1 translocation to increase activation of ISGs and subsequently exert an effect by partially suppressing DENV replication." (PMID 34394108, 2021). "In a previous report from our group, the same dengue cases analyzed here revealed a DENV-specific HMGB1 response in peripheral organs." (PMID 32486462, 2020). "DENV-specific high mobility group box 1 (HMGB1) response was also characterized within the CNS environment of fatal dengue cases." (PMID 32486462, 2020). "Aiming to better elucidate this topic, we investigated HMGB1 expression in peripheral organs of four patients who died from severe dengue." (PMID 29167501, 2017). "The participation of HMGB1 in dengue as an immune modulator has been reported since 2009, when Kamau and colleagues found that this cytokine can regulate the secretion of TNF-α, IL-6, IL-8 and IFN-α from DENV-infected dendritic cells." (PMID 29167501, 2017). "We observed several areas of HMGB1 and dengue RNA co-staining, which occurred within the cytoplasmic region of hepatocytes and Kupffer cells." (PMID 29167501, 2017). "While controls were negative and showed a regular structure of cardiomyocytes, dengue cases showed HMGB1 expression along the periphery of necrotic cardiac fibers." (PMID 29167501, 2017). "As suggested by our co-staining experiments, all four studied dengue fatal cases presented virus-specific HMGB1 signaling in their peripheral organs (liver, lung and heart)." (PMID 29167501, 2017). "For this reason, here we investigated the participation of HMGB1 in peripheral organs of dengue fatal cases in an attempt to better characterize dengue pathogenesis." (PMID 29167501, 2017). "The previous evaluations showed that tissue samples from dengue cases presented alterations that were in accordance with an ongoing HMGB1-mediated activity." (PMID 29167501, 2017). "Additional experiments of in situ hybridization allied to IHC revealed that dengue RNA and HMGB1 co-stain within the cytoplasmic region of immune cells." (PMID 29167501, 2017). "We observed that peripheral sites (liver, lung and heart) considered as relevant in the context of severe dengue were targeted by HMGB1-mediated signaling." (PMID 29167501, 2017). "Based on the analyses of dengue post-mortem samples, this report highlights the relevance of HMGB1 in dengue and brings novel considerations towards the immunopathogenesis of the disease." (PMID 29167501, 2017). "This work showed for the first time the in-situ characterization and the participation of HMGB1 in severe dengue." (PMID 29167501, 2017). "Allonso and coworkers showed that HMGB1 can be used as a biomarker for severe dengue prognosis and high HMGB1 levels were correlated with increased vascular permeability, intensity of symptoms and incidence of secondary infection." (PMID 27348219, 2016). "However, little is known about the participation of HMGB1 when considering human samples, especially in the context of severe dengue." (PMID 29167501, 2017).